ADAM5 (ADAM metallopeptidase domain 5 (pseudogene))
Description:
This is a non catalytic metalloprotease-like protein.
Synonyms: ADAM5P; tMDCII
Gene: Transcribed unitary pseudogene on chromosome 8 (39,314,591 to 39,417,378, forward strand). Ensembl gene ENSG00000196115.
Diseases named in the same sentence as ADAM5 in open-access papers:
ADAM5 is named in the same sentence as 6 diseases in open-access papers, as found by Europe PMC text mining. Sharing a sentence is not in itself a finding about the gene and the disease. The quoted sentences say what the papers report.
tumor (3 papers, 2013 to 2022). "On the other hand, ADAM5 was found to facilitate the invasion and migration of tumor." (PMID 33062410, 2020). "After multivariate Cox analysis, advanced tumor stage (HR: 2.34, 95% CI: 1.37–4.00, p = 0.002) and total deletion or one copy of the ADAM3A and ADAM5 pseudogenes (HR: 1.68, 95% CI: 1.07–2.66, p = 0.02) were found to be predictors of poor EFS." (PMID 36553675, 2022).
ADAM5 also shares sentences with these, for which no sentence is quoted: autoimmune disease (1 paper); cancer (1); male infertility (1); oropharynx cancer (1); psoriasis (1).